CRP (C-reactive protein)
Diseases named in the same sentence as CRP in open-access papers (continued):
Sharing a sentence is not in itself a finding about the gene and the disease.
infection (continued). "Serum amyloid A (SAA) is a non-specific inflammatory marker produced in the liver in response to infection, trauma, and other inflammatory states and has been hypothesized to be a more sensitive marker of inflammation over CRP for certain diseases." (PMID 26321888, 2015). "CRP is one of the widely used biomarkers for monitoring the course of infection and inflammation." (PMID 24669233, 2014). "IL-6 is a cytokine of the early host response to infection, preceding the increase of CRP." (PMID 25485809, 2014). "In particular, high levels of CRP in the first postoperative week are the normal postoperative course and could be interpreted as infection CRP only if their increase to levels of pathology persists during time." (PMID 24877114, 2014). "Previous studies that investigated the association between infection severity and CRP or PCT did not specifically explore these relationships in patients with impaired renal function exclusively." (PMID 25407928, 2014). "Similar observations could be made for other routine infection and inflammation markers such as C-reactive protein (CRP), procalcitonin (PCT), IL-6, and sCD14-ST." (PMID 25498125, 2014). "CRP acts as a stress protein and cannot be used to prove that infection is present." (PMID 24393388, 2014). "Recently, CRP has been proposed as a candidate biomarker for active infection with Mtb." (PMID 25375117, 2014). "In conclusion, this study suggests that in spite of its higher cost, PCT is not superior to CRP as an infection marker in terms of diagnostic value." (PMID 25407928, 2014). "The decline tendency of CRP levels may be partly due to the anti-inflammation and anti-infection effects of EN." (PMID 24719613, 2014). "Assessment of other low grade inflammation markers such as high-sensitivity CRP, could be informative as an indication for the severity of infection, and this needs to be assessed in future studies." (PMID 24576354, 2014). "The significantly lower RBC and Ht and higher CRP levels in the STG may represent secondary reactions to infection and different degrees of inflammation compared with the non-STG." (PMID 24522863, 2014). "The evaluation of CRP-levels, as the only biological marker for infection in this study, did show an informative value for the presence of any infection (versus no pathogen identified), as well as for the cause of the infection (viral vs. bacterial)." (PMID 24755844, 2014). "Likewise, indicators of infection as C reactive protein and α1-glycoprotein have been evaluated in some studies on iron supplementation." (PMID 25023784, 2014). "This study demonstrated that PCT is not superior to CRP for diagnostic accuracy, nor is it more reliably associated with infection severity considering renal function." (PMID 25407928, 2014). "In order to rule out infection and other immunological abnormalities as a possible cause of the enhanced inflammatory response, CRP and PCT levels were determined peri- and post-operatively." (PMID 25559834, 2014). "Thus, the kinetics of CRP make it a useful monitor for tracking the inflammatory response produced by infection, and the response to antibiotic treatment." (PMID 24484547, 2014). "The diagnostic value of CRP and PCT for predicting infection was compared using the ROC curve." (PMID 25407928, 2014). "An increase in C-reactive protein indicates inflammation, which is common in infection." (PMID 27355027, 2014). "PCT has the advantage of an earlier peak level upon infection, a better specificity and correlation to disease severity and clinical outcome as compared to routine biomarkers such as white blood cell count or C-reactive protein (CRP)." (PMID 25384060, 2014). "Therefore, the high sensitivity of CRP can be used in the later period after surgery as possible sign of infection (e.g., 2-3 weeks after surgery to 1-2 years or later), although the baseline values should be known." (PMID 24877114, 2014).
infection (continued). "For example, in strain KZ306, the WBC counts, the percentages of neutrophils, and the CRP levels were significantly greater on Days 4 and 8 after biofilm formation, compared with the controls samples, suggesting that the infection model was successfully established." (PMID 25551618, 2014). "Literature cited in this review supports the role of PCT as an adjunct clinical tool for determining the presence of an underlying infection in febrile pediatric patients and suggests that PCT may be a superior biomarker compared to C-reactive protein (CRP)." (PMID 27355024, 2014). "The infection was likely to be severe and prolonged, as suggested by low serum albumin levels and a rise in C-reactive protein to a maximum of 18.03mg/dl on day 24, though symptoms of infection in this patient may have been masked by glucocorticoid use." (PMID 24524438, 2014). "The study suggests that in spite of its higher cost, PCT is not superior to CRP as an infection marker in terms of diagnostic value." (PMID 25407928, 2014). "Among them, CRP is frequently used and is a good marker for infection." (PMID 24764729, 2014). "Since infection is a potent trigger of inflammation, we hypothesized that CRP levels at discharge would correlate with long-term mortality in septic patients and that the CRP/albumin ratio would be a better marker of prognosis than CRP alone." (PMID 23555017, 2013). "Also in Dutch adults, the strongest predictor of serum hepcidin was SF (R2 = .58 and R2 = .62 in adult men and women, respectively), followed by CRP, but infection/inflammation is much more common in our sample of Kenyan infants." (PMID 23460869, 2013). "CRP values correlated well with the severity of the infection." (PMID 24286072, 2013). "Early studies indicated that CRP bound to Plasmodium falciparum and P. yoelii sporozoite surface membranes and that CRP could protect rats from experimental infection with P. yoelii sporozoites." (PMID 24167754, 2013). "CRP concentration, with its rapid and cheap measurement, may be a good partner to refine the diagnosis of infection." (PMID 24286072, 2013). "A study using the methodology we based our study upon, found that daily CRP monitoring could be used as a marker of infection prediction." (PMID 23547830, 2013). "Regarding the subgroups, the CRP decreased faster 7 days postoperatively in the high-silver group (n = 9; 5 of them were from the infection group) compared to the low-silver group (n = 9; 4 of them were from the infection group)." (PMID 23819120, 2013). "We performed an additional analysis for independent predictors of bacterial infections excluding the obviously correlated infection markers fever, CRP and hsPCT from the model and detected mechanical ventilation and lymphocytopenia on admission as independent predictors." (PMID 24069356, 2013). "Several studies have shown the usefulness of PTX3 and CRP in assessing the severity of infection." (PMID 23341967, 2013). "CRP level and fever as infection parameters were both found to be significant." (PMID 24025668, 2013). "The serum albumin level was negatively correlated with the hs-CRP level in these patients, implying that the extent of the decline in the serum albumin level reflects the progress of the sub-clinical inflammation and/or infection." (PMID 24007461, 2013). "In addition, in patients with CRP levels >140 mg/L on the 4th postoperative day after rectal surgery with primary anastomosis, a 90.5% positive predictive value for postoperative infection was measured." (PMID 23409097, 2013). "It seems most likely therefore that waist:hip ratio is associated with an increased CRP responsiveness to injury through mechanisms independent of the degree of tissue damage or procedure related infection." (PMID 23391158, 2013). "It was subsequently demonstrated that CRP could protect mice from experimental infection with S. pneumoniae and that this effect was mediated in large part through activation of complement." (PMID 24167754, 2013).
infection (continued). "The relations that we observe appear to be independent of CRP level, suggesting that we are not observing a general association with other intercurrent infection or inflammation." (PMID 23442763, 2013). "We also hypothesized that CRP and PCT differ in this respect, so that CRP primarily predicts the course of local infection and PCT that of systemic infection and its adverse sequelae." (PMID 23762396, 2013). "CRP increases rapidly during infections and/or inflammation." (PMID 23941472, 2013). "The data, obtained during ICU-acquired fever and infections, suggest that CRP may be favoured over PCT courses in judging response to antibiotic treatment." (PMID 23762396, 2013). "Thus, apart from the stimulus by means of anoxia or infection, the amount of CRP rises in different degrees, being more accentuated in children that do not reach gestational maturity, probably due to the higher degree of stress to which they are submitted." (PMID 23401697, 2013). "These associations remained unaltered even after adjusting for age, sex, Sequential Organ Failure Assessment (SOFA) score, Charlson Comorbidity Index, renal replacement therapy, albumin, hemoglobin, lactate, C-reactive protein and infection sites in multivariable models." (PMID 24321201, 2013). "Only infants showing an elevated CRP were included into the infection group of the study." (PMID 23365583, 2013). "The CRP expression was higher in the cases with chronic stress, mainly in the cases with infection." (PMID 23401697, 2013). "Although we have shown that West-Africans do not exhibit inherently high circulating CRP levels it is not possible with this study design to conclude on the effect of genes, diet, exercise, smoking, alcohol consumption, or unmeasured infections on CRP levels in West-African populations." (PMID 23922912, 2013). "We included CRP as a potential biomarker for presence and fatal outcome of S. aureus bacteremia as this marker is frequently used in clinical practice to determine and monitor inflammation and infection in general." (PMID 23520553, 2013). "In more than half of the infants of the infection group, a normalizing blood flow (continous flow) could be observed at the same day as CRP values decreased or even a day before." (PMID 23365583, 2013). "CRP concentrations can also be used as a marker of infection in neutropenic patients." (PMID 24286072, 2013). "The threshold for CRP at D7 to decide on the resolution of infection only is about 21 mg/L." (PMID 23762396, 2013). "High CRP levels are usually associated with an ongoing infection in patients with SLE, although they have been also associated with serositis, independently of the existence of an infection." (PMID 23557114, 2013). "Our data suggest that local factors that affect wound healing, such as tissue necrosis and infection may be better reflected by the systemic CRP levels than any other inflammatory cytokine." (PMID 24358275, 2013). "In addition to C-reactive protein, proinflammatory cytokines are known to play important roles in porcine immune response to infection." (PMID 23326551, 2013). "The same group validated this CRP cut-off as a predictor of infection in a prospective study." (PMID 24286072, 2013). "Several reports suggested that PCT should replace CRP as a marker of infection in the ICU setting." (PMID 23547830, 2013). "Schmit and Vincent reported the time course of CRP in 50 septic patients with adequate (n = 24) or inadequate (n = 18) empiric antibiotherapy and in surgical patients who needed reoperation for uncontrolled infection (n = 8)." (PMID 24286072, 2013). "Routine blood tests, especially elevated CRP (C-reactive protein) and/or leukocyte count, may suggest a diagnosis of infection (but are unhelpful in the early postoperative phase as they will be raised for around 14 days after surgery)." (PMID 24288493, 2013). "P. acnes shunt infections typically are indolent and present with normal serum CRP levels." (PMID 24308006, 2013).
infection (continued). "The sensible mathematical model of the latent diagnostic classification, using individuals’ values of CRP, DD and PCT, was able to identify a subset of patients attended in the ER with suspicion of infection and with clear differences in clinical status, microbiological profile and 28-day mortality." (PMID 24050481, 2013). "The serum concentration of CRP rises as much as 1000-fold in immediate response to cytokines or chemical mediators released in various pathological conditions, including acute inflammation, infection, tissue or cell necrosis, and some malignancies." (PMID 22857740, 2012). "The routine ordering of CRP for children with infections is based on weak evidence." (PMID 22943554, 2012). "Three biomarkers and 2 outcomes could be included in the meta-analysis: 11 studies provided data on CRP and documented infection." (PMID 22257704, 2012). "The increase of CRP in CSF and blood is indicative of invasive infection." (PMID 23483792, 2012). "When analyzed from a clinical perspective the majority of these patients presented with mild and local infections with low C-reactive protein (CRP) and the samples were obtained late in the course of the infection as reflected by an elevated mean draw index (0.64)." (PMID 22496797, 2012). "However, since the decision to administer antibiotics before operation and outcome was critically influenced by presence of severe infection at admission, which would be reflected in an elevated CRP, outcome was reanalyzed according to CRP at admission." (PMID 23193986, 2012). "We found that routine CRP ordering for diagnostic purposes for these infections failed to inform decision-making in the majority of cases while inflating hospital bills by $26,715.9." (PMID 22943554, 2012). "In addition, sTREM-1 levels can reflect the infection status more accurately and more specifically than can CRP and PCT levels." (PMID 22809118, 2012). "MDTH increased as the infection became more disseminated, which was most evident during the first half of the hospitalization period, and was paralleled by increased CRP and hospitalization duration." (PMID 22496797, 2012). "Despite this, an interest in CRP as an infection monitoring tool in the perioperative setting has increased since it was reported that in values higher than 140 mg/L on the postopertaive day (POD) 3-4 it well predicted infectious complications after colorectal surgery." (PMID 23275327, 2012). "Moreover, we tried to compare its discriminating power with other biomarkers, such as WBC count and CRP serum levels, during an episode of suspected infection." (PMID 23043618, 2012). "Data were available for meta-analysis for CRP for microbiologically or clinically documented infection; for PCT assessing microbiologically or clinically documented infection; and IL6 reporting microbiologically or clinically documented infection, and gram negative bacteremia." (PMID 22257704, 2012). "Laboratory markers such as C-reactive protein, erythrocyte sedimentation rate, and white blood count are sensitive markers of inflammation and plausible infection, but they are unable to localize the exact site of infection and they are associated with low specificity." (PMID 22607715, 2012). "Serum CRP was quantified 5 days, 3 weeks, 3 months and 6 months post infection." (PMID 23240022, 2012). "The increase in the serum concentration of CRP is rather slow during the first 24-48 hr of infection and this may negatively affect the sensitivity of the test." (PMID 23493845, 2012). "No studies or recommendations were found addressing the benefits and harms of screening asymptomatic people for alanine aminotransferase (ALAT), aspartate aminotransferase (ASAT), infection parameters (C-reactive protein, sedimentation rate or white blood cells), fitness ratings or fat percentages." (PMID 22479429, 2012).
infection (continued). "Differences between genders in CRP levels in relation to outcome may also represent a part of a gender-related inflammatory response pattern or be related to differences in source of infection." (PMID 22793786, 2012). "Thus, CRP levels were generally higher during active infection compared to convalescent samples, where HIV-1 was seen to increase." (PMID 22745697, 2012). "In these situations, there may be prolonged wound drainage, radiographic changes, if the infection is chronic, or abnormal serology (elevated C-reactive protein and erythrocyte sedimentation rates) and positive cultures on joint aspiration." (PMID 22698085, 2012). "According to the diagnostic criteria, all patients displayed at least one of the hallmarks of the classical presentation of APN (high fever, costovertebral pain and/or tenderness, signs or history of recent UTI), plus at least one sign of infection/inflammation (high CRP level, increase in WBCs)." (PMID 22171968, 2011). "A pronounced rise of the CRP level on the third postoperative day after arthroplasty is normal, but a further rise at one to 2 weeks suggests the presence of a serious complication, including infection." (PMID 24977067, 2011). "Also, there were subtle differences between the reactions of CRP, pigMAP and Hp to the different infections; for example CRP reacted more quickly in S. suis infected pigs than pigMAP and - - was the only APP induced by PRRSV." (PMID 21414190, 2011). "Serum procalcitonin, C-reactive protein and white blood cell levels are elevated in patients under hypothermia, irrespective of an underlying infection." (PMID 21291523, 2011). "CRP is one of the wildly used biomarkers for monitoring the course of infection and inflammation." (PMID 21714897, 2011). "It has been shown that a single CRP measurement helps in the diagnosis of infection with some controversy concerning prognosis, and that serial determinations are useful in the prediction of infection as well as in monitoring its response to treatment." (PMID 21762483, 2011). "CRP rises up to 50,000 fold in acute inflammation, such as infection." (PMID 21430962, 2011). "To estimate the remaining 71 kinetic parameters, we generated test data by incubating human blood under normal and infection-inflammation conditions with beads coated with PC or GlcNAc followed by immunodetection of the deposited CRP, C4, C3 and C4BP in time series." (PMID 21283780, 2011). "The established biological markers of inflammation (leukocytes, C-reactive protein) may often be influenced by parameters other than infection and may only be slowly released during progression of an infection." (PMID 21633539, 2011). "Taking into account data from other studies, it seems that CRP could be used as an early marker, as early as D3, of infection response to antibiotics." (PMID 21762483, 2011). "However, the level of CRP, usually chosen as the main marker of infection, was only mildly elevated in 3 cases (2 testing positive at FDG-PET/CT scan and 1 testing negative)." (PMID 21957932, 2011). "Since early CRP changes correlate with the adequacy of antibiotic therapy and to the bacterial load, at least in VAP patients, it seems that the CRP course could be used as a surrogate marker of the clinical course of infection." (PMID 21762483, 2011). "C-reactive protein (CRP) is a widely studied general marker of inflammation and infection." (PMID 21687625, 2011). "CRP is an acute-phase protein known as a biomarker for inflammation, and has been traditionally used to detect and predict the outcome of infections, inflammatory, necrotic processes as well as monitor clinical disease activity together with efficacy of treatment." (PMID 21679442, 2011). "The concentrations of CRP levels in healthy adults are normally less than 10 mg/L and serum levels of CRP may increase over 1000-fold following inflammation or infection." (PMID 21827658, 2011).